CD4 (CD4 molecule)
Diseases named in the same sentence as CD4 in open-access papers (continued):
Sharing a sentence is not in itself a finding about the gene and the disease.
infection (continued). "However, 8 weeks after infection, SV/129 mice displayed a significant increase in the percentage of splenic CD4+ T cells with the capacity to secrete IFN-γ or TNF-α (at least p ≤ 0.05)." (PMID 30881923, 2019). "Targeting the ability of macrophages to mediate highly efficient HIV trans infection of CD4+ T cells could be a promising therapeutic approach for eliminating the viral reservoir." (PMID 30871222, 2019). "Toxoplasma gondii induces a strong CD4 T cell response that is a major source of IFNγ during both acute, as well as chronic infection, and is similar to what has been observed in other infections." (PMID 31119107, 2019). "In addition, iTbx21−/− CD4+ T cells were purified and adoptively transferred into infection-matched recipient mice at day 7 post LCMV infection." (PMID 30984183, 2019). "However, some EC experience CD4+ T cell loss and/or lose their ability to control HIV-1 over the course of infection." (PMID 31001238, 2019). "We investigated whether chemokine levels in PHI could predict CD4+ T-cell count at 1-year-infection, using a threshold of 500 cells/μL for distinguishing CD4+ T-cell count groups." (PMID 31836011, 2019). "Indeed, the IFN-γ positive CD8+ T cells in spleen of PyNL infected mouse was about three-fold more than that of CD4+ T cells in day 16 after the infection." (PMID 31608052, 2019). "First, the LAg assay has a shorter MDRI and may have classified many specimens as recent, which were from persons whose infections where in the phase where a transient increased drop in CD4+ T cell counts occurs prior to reaching viral set-point." (PMID 31125356, 2019). "The total CD4+ T cell count was decreased in the P group during the first 4 weeks of Pc infection and was then increased to high levels at week 11 and maintained during the remaining course of infection." (PMID 31718574, 2019). "Importantly, the presence of increased numbers of IAV-specific memory CD4 T cells prior to seasonal infection correlates with improved clinical outcome in human longitudinal studies." (PMID 31412088, 2019). "In all three CD4+ cell count subgroups and in the PSM analysis with matching baseline CD4+ cell count, the association between CTX use and reduced TM infection was consistently observed, indicating baseline CD4+ cell count does not affect the relationship of CTX use and reduced TM infection." (PMID 31851879, 2019). "Given that STLV-1 and SFV may compete for CD4+ T-cells infection in vivo, we investigated here, in a series of 36 animals, whether STLV-1 co-infection impacted or not SFV proviral load in the blood and in the saliva." (PMID 30273350, 2018). "It is known that cytokines produced by type 1 helper CD4+ T cells are able to control infection." (PMID 29545782, 2018). "In contrast, the percentage of DNGR-1+ CD4+ DCs varied during the course of infection." (PMID 29472618, 2018). "Whether these additional functions also impact DC/Macrophages-mediated cis- or trans-infection of CD4+ T cells remains poorly characterized." (PMID 30055632, 2018). "In this study, we focus on the ZIKV-reactive CD4+T cell response in a mouse model of infection." (PMID 30212537, 2018). "In addition, very little is known about CD4+ or CD8+ memory T cell subset distribution in Ss infection." (PMID 29795573, 2018). "In addition, HIV can promote NF-κB, AP1, and NFAT translocation to the nucleus and actin cytoskeleton rearrangement, including activation of cofilin, which reorganizes cortical actin barriers that restrict infection in primary CD4 T cells." (PMID 29970186, 2018). "The newly infected, activated CD4+ T cells would in turn produce virus to infect other cells, and in this manner, a limited chain of new infections could continue for some time." (PMID 29378657, 2018). "One expectation of this study was that by reducing immune activation, the availability of activated CD4+ T cells that are a preferred target of infection would also be reduced and therefore reservoir seeding could be impacted." (PMID 30161247, 2018).
infection (continued). "However, by day 21 post-infection, the frequency of CD4+ T-cells in the genital tract of wild-type and TLR3-/- mice was significantly different." (PMID 29624589, 2018). "CD4+ T cell populations in PBMCs at 8 days post-infection with Mtb H37Ra." (PMID 30204787, 2018). "Thus we stratified our data by subtype A, C and D infection to remove confounding by subtype virulence and to access the influence of env genetic diversity in plasma on the slope of CD4 T cell declines during disease progression." (PMID 29346424, 2018). "DN T cells have been shown to produce IL-17A earlier than CD4 T cells and demonstrate features of antigen-experienced T cells including lower threshold of stimulation, proliferation, cytokine production, and also contribute to clearance of infection." (PMID 30386336, 2018). "HIV efficiently infects activated CD4+ T-cells leading to a productive infection state." (PMID 29997630, 2018). "The substance prevented infection of human CD4+ T-cell lines AA2 and H9 with HIV-1 at concentration of 25 μg/mL as well as the cell-to-cell virus spread in H9 cells continuously infected with HIV-1 were determined by the measurement of reverse transcriptase activity and p24 content in cell cultures." (PMID 29757986, 2018). "However, in our previous studies, we found that NPMs progressed to AIDS much more slowly than rhesus macaques, and maintained superior CD4+ T cell homeostasis during SIVmac239 infection." (PMID 30210504, 2018). "The work presented here shows that an increased capacity of CD4+ T cells to bind foreign-pMHC does not translate into an increased response upon immunization or pathogenic infection in old mice." (PMID 29864157, 2018). "Collectively, these data would suggest that the cytotoxic program of CD4 T cells might be impaired in chronic HCV-infection due to TGF-beta signaling." (PMID 30453612, 2018). "CD4 T cell-sufficient and -deficient mice showed similar frequency and number of CD8 T cells specific for the dominant DbLT359 epitope in both the brain and spleen in acutely [day 8 post-infection (p.i.)] and persistently (day 30 p.i.)infected mice." (PMID 30372487, 2018). "Furthermore, this study demonstrates infection-induced NK1.1+ CD4+ T cells are critically reliant on MHC-II antigen presentation for their development." (PMID 30374346, 2018). "In addition, infection with TK− HSV-2 provided local, long-term protection against a secondary infection with wild-type HSV-2 based on the formation of CD4 TRM cells, which were retained mainly among memory lymphocyte clusters (MLCs)." (PMID 30147701, 2018). "To determine if the epitope specific CD4+T cell response was preserved into memory we next repeated our infection of C57BL/6J mice with an IV injection with 1x106 FFU of ZIKV and waited 30 days before harvesting the spleens and performing the intracellular cytokine stain." (PMID 30212537, 2018). "MΦ-mediated HIV-1 trans infection enhances virus production from CD4+ T cells in SN." (PMID 29643243, 2018). "On the other side, limited infection of Tcm and Tscm CD4+ T cells in VNPs has been reported, suggesting that host factors rather than specific viral properties may allow VNPs to dodge HIV-1 pathogenesis and chronic immune activation." (PMID 29593044, 2018). "Concurrently, Bcl-6 protein level was remarkably lower in Uba3-deficient CD4+ T cells than in Uba3-sufficient counterparts at day 7 of infection, and the proportion of IL-21-producing CD4+ T cells in the spleen was also found to be lower in Uba3ΔT mice at this time." (PMID 30462731, 2018). "From this hypothesis, these authors suggest that endocytosis of virus particles is the main mechanism used by HIV-1 for cell-to-cell transfer and infection of primary CD4+ T cells." (PMID 29515578, 2018). "However, HIV can escape host immune responses and drug treatment by establishing a reversibly silent ("latent") infection in CD4+ T cells." (PMID 30440043, 2018).
infection (continued). "Finding cases where the CD4+ T cell count improved, at least temporarily, after superinfection, would indicate that at least one of the complicating factors that allow such an effect are indeed at work in the infection." (PMID 30083143, 2018). "Those with CAP had higher median white cell count and CD4 count than the other two infections." (PMID 30107791, 2018). "However, vvIBDV infection led to a significant decrease in the number of CD4+ IEL at three and seven and CD8ß+ IEL at seven dpi (P < 0.05)." (PMID 29390031, 2018). "To investigate whether FRCs mediate trans-infection of primary memory CD4+ T cells, we used PHA-stimulated peripheral blood lymphocytes (PBLs) as target cells." (PMID 29934525, 2018). "Therefore, we next quantified the recognition by A32 and infection of these p24+ CD4+ cells by RNA-flow FISH (dark gray box)." (PMID 29559570, 2018). "Recent clinical data showing increased ex vivo infection of CD4+ T-cells in PBMCs from women on DMPA-IM are in support of our findings and suggest that our ex vivo findings may be of clinical relevance." (PMID 29698514, 2018). "Thus, in chronically MAA-infected mice NO produced by Gr-1intCD11bhiCD11cint M-MDSC appears to exacerbate the infection and affects specifically CD4+ T cells." (PMID 30386330, 2018). "Interestingly, CD4 TRM cells were also found in the flank skin far from the primary infection site in the ear." (PMID 30147701, 2018). "However, for 129P2Sv/ev mice, depletion of CD4+ T cells late after PbA infection prevented the development of ECM." (PMID 30250468, 2018). "Alternatively, HIV-1-infected cells represent targets once infection is established, although in this case, CD4 downregulation and Tetherin/BST-2 antagonism could reduce HIV envelope ADCC-mediating epitope exposure." (PMID 29651286, 2018). "HIV‐1 is able to infect DC; however, infection levels are much lower than in CD4+ T‐cells." (PMID 30123959, 2018). "However, sorted CD14+ myeloid cells isolated 20 h post-infection from 5 HIV-infected cervical explants tested all transmitted HIV to activated CD4+ T cells, while only 1 sample of sorted CD4+ T cells did." (PMID 30532754, 2018). "Against this, we observe an expansion of Ag85-specific CD4+ T cells with infection, alterations on the T cell activation profile that are more exuberant in the transgenic over the non-transgenic cells and more IFNγ+ and TNF+ CD4+ T cells in the transgenic compartment." (PMID 29499041, 2018). "Furthermore, CD4+ T cells elicited by a tetravalent live attenuated DENV vaccine (TV005) recognize epitopes identified in natural infection, and dominantly recognize the capsid, NS2A, and NS5 proteins." (PMID 30340377, 2018). "sPLA2-X has been shown to inhibit the replication of tropic HIV-1 CCR and CXCR in human CD4+ T cells (T-helper cells, which are white blood cells that play a principal role in protecting the body from infection) and potentially reduce gene transfer among HIV-1 envelope pseudotyped viral vectors." (PMID 30034176, 2018). "This was the first indication that EC, which physiologically serve as antigen-presenting cells to T cells, particularly in lymphoid microenvironments, might play a significant role in infection of resting CD4+ T cells in vivo." (PMID 30285810, 2018). "Antibody depletion of CD4+ T cells in PbA-infected F1 (129/Ola X C57BL/6J), CBA/Ca, and C57BL/6 mice prevented the development of ECM when conducted before or early in the infection, suggesting an essential role for CD4+ T cells in the initiation of ECM pathogenesis." (PMID 30250468, 2018). "Infection of primary CD4+ T cells with HIV-1 coincides with an increase in glycolysis." (PMID 29518929, 2018). "Establishment of HIV-1 latency may be the consequence of infection in CD4+ T cells within a narrow window of time after activation." (PMID 30013105, 2018).
infection (continued). "This difference was associated with global CD4+ T cell preservation and greater interferon gamma (IFN-γ) mRNA expression, but not cytotoxic T lymphocyte responses in co-infected cats relative to cats with single FIV infection." (PMID 29677149, 2018). "However, other endogenous modifications are also plausible in the CD4+T cell compartment, as was previously demonstrated in parasitic models of infection." (PMID 30319642, 2018). "Indeed, human eosinophils express CD4 and CXCR4 and are susceptible to infection by CXCR4-tropic HIV-1, according to evidence in vitro." (PMID 29619379, 2018). "This difference in IFN-γ producing CD4 T cell population disappeared by day 10, and with resolution of infection (day 15) there was a comparative increase in the Plasmodium-responsive, IFN-γ expressing memory CD4 T cell population in the pmif RNA immunized group." (PMID 30006528, 2018). "Reduced secretion of IL-6 during antigen presentation may lead to development of CD4+ Th2-dependent response which is important during infection of mucous membranes." (PMID 29872440, 2018). "Although early studies suggested that NP and HA were the major source of epitopes recognized by CD4 T cells after infection, more recent studies by our laboratory have demonstrated that epitope specificity can be quite broad and depends on the selectivity imposed by MHC class II molecules." (PMID 29681900, 2018). "Overall, results indicate that, at 7 days post-infection, viral production from initially unactivated CD4+ T-cells is significantly higher upon exposure to supernatants derived from infected MDMs treated with 1 ng/ml MIF, compared to exposure to supernatants derived from uninfected MDMs." (PMID 29997630, 2018). "A role for CD4+ T cells in ECM pathogenesis was also supported by experiments where PbA infection of CD4-deficient mice did not lead to the development of ECM." (PMID 30250468, 2018). "Enhancement of IFNγ responses in the 6mo-cases could result from infection-induced pre-activation of NK cells, cytokine-induced memory-like NK cells generation, and/or help from CD4+ T cells." (PMID 29520269, 2018). "In fact, neutralizing antibody titers were higher in mice with ONX 0914 treatment, an observation that might be attributed to maintained survival of CD4+ T cells during infection in response to i-proteasome inhibition." (PMID 30546359, 2018). "Infection with blood-stage PbAmif− parasites, when compared to PbAWT parasites, is associated with lower circulating levels of IFN-γ and increased numbers of Plasmodium-responsive CD4 T cells that develop into memory precursor CD4 T cells." (PMID 30006528, 2018). "To further assess whether early antigenic or inflammatory signals are responsible for the induction of IL-10+IL-21+Tfh cells during persistent infection, we transiently depleted CD4 T cells at the time of infection." (PMID 30487586, 2018). "CD4 T lymphocytes are critical mediators of the adaptive immune response to infection." (PMID 29734372, 2018). "The frequency of circulating CD4+Glut1+ T cells and the rs1385129 SLC2A1 SNP may predict the rate of HIV disease progression and CD4+ T cell recovery in untreated and treated infection, respectively." (PMID 29867928, 2018). "One question that has not yet been addressed is whether these diverse peptide specificities that are elicited by infection persist in the CD4 T cells that home to the lung after infection." (PMID 29681900, 2018). "Of note, in addition to CD4+ T cells, also ACC1-deficient CD8+ T cells showed a strong reduction in their production of IFN-γ, suggesting that de novo lipid synthesis is also required in these cells to mount effective effector responses during infection." (PMID 29675017, 2018). "While follicular CD4 T cells are by default activated and highly permissive to infection, the activation status and thus permissiveness of extrafollicular CD4 T cells might vary, and might be driven by the amount of virus present in the EF compartment." (PMID 30335747, 2018).
infection (continued). "Besides, the ratio of CD4+ T cells to CD8+ T cells decreased for X4550(pYA3334-P-SspH2-EscI) infection." (PMID 29523140, 2018). "However, some bNAbs were also shown to inhibit infection or trans-infection from monocyte-derived or plasmacytoid dendritic cells to CD4+ T cells and vice versa." (PMID 30055632, 2018). "However CD4+ T cell-derived cytokines can have anti-viral effects, and CD4+ T cell engagement would reduce the migration of infected myeloid cells and so their capacity to spread infection." (PMID 29447285, 2018). "Our results identify a novel human memory CD4 T cell subset with an unorthodox, TN-like phenotype, which is involved in the human immune response to mycobacteria, and which correlates with the presence of active TB disease during infection by M. tuberculosis." (PMID 29875774, 2018). "Moreover, our preliminary data showed similar expression of cytotoxic molecules in MCMV specific CD4 T cells from CD4-ER-Cre Eomesfl/fl mice in which Eomes was deleted specifically in CD4 T cells prior to infection (unpublished observation)." (PMID 30044874, 2018). "Furthermore, failure to clear infection at 21 dpi was associated with a lower number of total and activated CD69+ CD4+ T cells in infected mice than in control and/or infected mice at 7 dpi (P < 0.0001 and P = 0.03, respectively)." (PMID 29610255, 2018). "Given the importance of CD8+ T cells in ECM pathogenesis and the well-established role for CD4+ T cells in helping CD8+ T cells in many infection models, the requirement for CD4+ T cells in ECM pathogenesis may reflect a similar helper role." (PMID 30250468, 2018). "Here we report the discovery of a novel ligand that can inhibit HIV-1 entry and infection via CD4." (PMID 30463393, 2018). "Thus, infection with the fbp1Δ mutant seems to skew CD4+ T cell polarization toward Th1 and Th17 responses and diminished Th2 differentiation." (PMID 29317510, 2018). "Studies on bacterial survival and CD4+ T cell responses after infection of mice with M. avium revealed that the result of infections and immunopathology strongly depended on the subspecies and strain of M. avium investigated and the route of infection." (PMID 30386330, 2018). "We also explored whether CD4+ T-cell viability and infection percentages were affected by the addition of supernatants derived from MDMs treated under the different MIF conditions." (PMID 29997630, 2018). "Thus, there was a significant increase in inflammatory cells (monocyte/macrophages and granulocytes) in BALB/c mice early after infection with B. pseudomallei 1106a, but a significant CD4+ T cell response to the pathogen later in C57BL/6 mice." (PMID 30500862, 2018). "However, anti-CD4 antibodies prevent infection of CD4 T cells by FDC-bound HIV-ICs ex vivo, suggesting that the CD4 binding site on gp120 must become at least temporarily exposed on FDCs." (PMID 29422894, 2018). "However, by 10 days post infection it was clear that these cell populations were either drastically reduced in numbers or became totally depleted, leaving the CD4+ T cells to execute the major task of cytokine production." (PMID 30333827, 2018). "On the other hand, on-target activation of CD4+ T cells by CD3 scFv could have the potential to spread infection, which highlights the need to protect uninfected cells by administration with effective ART, ideally including an integrase inhibitor." (PMID 30564246, 2018). "The same comparisons for Groups 5 and 6, receiving ART since week 1 post-infection, with CD4+ T-cell loss not as pronounced as in the groups initiating ART in the chronic phase, were significant for CD4+ T cells but not for CM CD4+ T cells." (PMID 30161247, 2018). "We also demonstrated that LEC stimulation promotes infection in activated CD4+ T cells." (PMID 30285810, 2018). "Thus while CD4+ T cells are important for host defence, viral evasion limits their capacity to act alone in controlling infection." (PMID 29447285, 2018).